THEM6 (thioesterase superfamily member 6)
Synonyms: C8orf55; DSCD75
Tractability: Antibody: UniProt places it where antibodies can reach, with high confidence; UniProt predicts a signal peptide or a membrane-spanning region; its Gene Ontology location is reachable by antibodies, with medium confidence. PROTAC: ubiquitination databases record sites on it; its protein half-life has been measured.
Gene: Protein-coding gene on chromosome 8 (142,727,191 to 142,736,938, forward strand). Ensembl gene ENSG00000130193.
Subcellular location: Secreted
Subcellular location (Human Protein Atlas): Cytosol; Nuclear speckles; Predicted to be secreted
Gene Ontology:
Cellular component: extracellular region
Genetic constraint (gnomAD): Loss-of-function variants: 10 observed, 6.04 expected, observed/expected ratio (o/e) 1.65, 90% interval 0.95 to 1.95. That is too few expected variants to judge how well the gene tolerates losing a copy. Missense variants: 317 observed, 192.53 expected, observed/expected ratio (o/e) 1.65, 90% interval 1.5 to 1.81. Synonymous variants: 160 observed, 96.79 expected, observed/expected ratio (o/e) 1.65, 90% interval 1.45 to 1.88.
Homologues: Orthologues: chimpanzee THEM6 (100% identical), macaque THEM6 (98% identical), pig THEM6 (88% identical), mouse Them6 (88% identical), dog THEM6 (87% identical), rat Them6 (86% identical), guinea pig THEM6 (79% identical), tropical clawed frog them6 (58% identical), zebrafish THEM6 (48% identical), zebrafish them6 (46% identical), Drosophila melanogaster CG4666 (33% identical), Drosophila melanogaster CG4660 (33% identical).
Diseases named in the same sentence as THEM6 in open-access papers:
THEM6 is named in the same sentence as 16 diseases in open-access papers, as found by Europe PMC text mining. Sharing a sentence is not in itself a finding about the gene and the disease. The quoted sentences say what the papers report.
prostate carcinoma (5 papers, 2011 to 2024). A carcinoma that arises from epithelial cells of the prostate gland. "The overexpression of THEM6 has also been shown to promote the growth and migration of prostate cancer." (PMID 39596181, 2024). "Further proteomics analysis of THEM6‐depleted prostate cancer cells revealed a significant downregulation of a large cluster of ER‐related membrane proteins." (PMID 35107853, 2022). "Med., that shows that THEM6 reprograms lipid metabolism to support resistance to androgen‐deprivation therapy, and is a promising target for the treatment of castration‐resistant prostate cancer." (PMID 35107853, 2022). "In addition, analysis based on the CCLE database discovered that THEM6 was also highly expressed in many cancer cell lines, such as gastric cancer, prostate cancer, and BLCA." (PMID 35909893, 2022).
breast carcinoma (4 papers, 2022 to 2024). "Our findings indicate that the overexpression of THEM6, which is linked to the development of breast cancer, is a predictor of a poor prognosis and has an impact on the degree of immune cell infiltration." (PMID 38081884, 2023). "To validate these findings, we also assessed the metabolic impact of THEM6 loss in the highly lipogenic and steroidogenic breast cancer MCF‐7 cell line." (PMID 35014179, 2022). "Recently, the human THEM6 gene has become a research hotspot, as its expression is higher in colorectal, gastric, and breast cancer tissues than in normal tissues, and it has been considered a potential biomarker for these cancers." (PMID 39596181, 2024). "We further performed qRT-PCR, immunoblotting and IHC assays to validate the expression of THEM6 in various breast cancer cells and tissues." (PMID 38081884, 2023). "To investigate the expression of three genes, NR1H3, PLEKHA4, and THEM6, in breast carcinoma, we analyzed multiple independent cohorts, including three GEO cohorts as well as the cBioPortal database." (PMID 38081884, 2023). "qRT-PCR and Western blotting experiments demonstrated a general upregulation of THEM6 expression in breast carcinoma cells." (PMID 38081884, 2023). "We further investigated the relationship between THEM6 expression, prognostic value, and immunology in breast cancer through bioinformatics." (PMID 38081884, 2023). "The results revealed a significant elevation of THEM6 expression levels in several carcinoma types, including breast carcinoma (BRCA), cholangiocarcinoma (CHOL), and paraneoplastic tissues." (PMID 38081884, 2023). "In vitro studies indicated that THEM6 increased proliferation, invasion, and inhibited apoptosis of breast carcinoma cells, while also affecting the cell cycle and promoting cancer progression." (PMID 38081884, 2023). "IHC showed that THEM6 was expressed in both breast cancer tissues and para-cancer tissues, but its expression level was significantly higher in carcinoma tissues." (PMID 38081884, 2023). "The results of the Transwell experiment revealed a significant reduction in the invasive ability of both breast carcinoma cells after THEM6 knockdown." (PMID 38081884, 2023). "An earlier study using TMA included 14 tumor tissues and corresponding normal tissues which showed a high expression of THEM6 in colorectal cancer, gastric cancer, and breast cancer, and it was positively correlated with the progression of these cancers." (PMID 35909893, 2022). "Notably, the protein level of THEM6 was higher in other breast cancer cell lines compared to MCF-10A cells, with MCF-10A serving as the control." (PMID 38081884, 2023). "Additionally, apoptosis experiments showed that knockdown of THEM6 increased the apoptosis of breast cancer cells and inhibited cell survival." (PMID 38081884, 2023). "Therefore, it is hypothesized that knockdown of THEM6 may impact the breast cancer cell cycle, particularly the G0/G1 phase." (PMID 38081884, 2023). "Thus, THEM6 appears to promote the development of breast carcinoma." (PMID 38081884, 2023). "Additionally, western blotting revealed THEM6 protein expression in both MCF-10A and breast cancer cells." (PMID 38081884, 2023).
prostate adenocarcinoma (2 papers, 2022). "Using prostate adenocarcinoma (PRAD) TCGA dataset, the authors were able to establish a correlation between THEM6 and expression of several enzymes involved in the late steps of sterol biosynthesis." (PMID 35107853, 2022).
bladder cancer (1 paper, 2022). "However, prior research emphasized on its regulatory role merely, we aim to investigate the effect of THEM6 gene on the immunological role and its relationship with molecular subtype in bladder cancer (BLCA)." (PMID 35909893, 2022). "THEM6 also has good performance in predicting the molecular subtype and ICB therapeutic effect of bladder cancer." (PMID 35909893, 2022). "This study showed that THEM6 can form a noninflammatory TME, suggesting that the application of THEM6 inhibitor may recover TME immune response and normalize cancer immunotherapy in bladder cancer." (PMID 35909893, 2022).
breast neoplasm (1 paper, 2023). A benign or malignant neoplasm of the breast parenchyma. "Relative expression levels of THEM6 were assessed in various breast neoplasm cell lines using qRT-PCR." (PMID 38081884, 2023).
colon cancer (1 paper, 2022). "THEM6, formerly c8orf55, was originally discovered as a potential biomarker for colon cancer in a proteomic‐based analysis of human samples." (PMID 35014179, 2022). "Interestingly, overexpression of thioesterase superfamily member 6 (THEM6/c8orf55) has been reported in several cancer types in a proteomic study focusing on the identification of colon cancer biomarkers." (PMID 35014179, 2022).
mastitis (1 paper, 2024). Inflammation of breast tissue during lactation or postpartum due to an obstructed duct or infection. "Among them, cnvr_137 contains genes such as LY6D, LYNX1, LYPD2, SLURP1,THEM6, PSCA, TSNARE1, and ARC associated to clinical mastitis in US Holstein dairy cows." (PMID 38771855, 2024).
triple-negative breast carcinoma (1 paper, 2023). An invasive breast carcinoma which is negative for expression of estrogen receptor (ER), progesterone receptor (PR), and human epidermal growth factor receptor 2 (HER2). "The results demonstrated that knocking down the THEM6 gene inhibited the recruitment ability of triple-negative breast cancer cells to macrophage THP1 through observational counting." (PMID 38081884, 2023). "Furthermore, we observed that THEM6 expression was greater in triple-negative breast carcinoma tissues than in non-triple-negative breast carcinoma tissues." (PMID 38081884, 2023).
tumor (6 papers, 2022 to 2024). "Functional studies found that knocking out THEM6 inhibits tumor growth and that high levels of THEM6 are associated with poor clinical outcomes and elevated UPR activation levels." (PMID 39596181, 2024). "Biological functional analyses revealed that THEM6 was associated with tumor progression and pathogenesis." (PMID 38081884, 2023). "In vivo, loss of THEM6 significantly reduced tumour volume in a CRPC model of 22rv1‐derived orthografts (assessed by ultrasonography)." (PMID 35014179, 2022). "In addition to decreased tumour size, THEM6‐deficient orthografts exhibited large necrotic areas and decreased cellularity, especially under ADT conditions (Fig EV1C)." (PMID 35014179, 2022). "Furthermore, high THEM6 expression was associated with poor clinical tumour parameters, such as enhanced tumour proliferation and metastatic dissemination, and correlated with shortened overall and disease‐free patient survival." (PMID 35014179, 2022). "To complement the use of the CRPC models, we tested whether THEM6 loss would also sensitise PCa tumours to acute ADT treatment." (PMID 35014179, 2022). "However, step 2 (cancer antigen presentation) was upregulated, which might be explained by the increased number of tumor neoantigen caused by the high expression of THEM6." (PMID 35909893, 2022). "We analyzed the relationship between the expression level of THEM6 and the tumor immune microenvironment." (PMID 38081884, 2023). "THEM6 protein expression was found to correlate with tumor type, Ki67 expression level, and TNM stage." (PMID 38081884, 2023). "It was found that there was a higher expression of THEM6 in most tumor tissues (such as ACC, BLCA, BRCA, CHOL, COAD, ESCA, LIHC, and UCEC) when compared to that in normal paracancerous tissues." (PMID 35909893, 2022). "The higher expression of THEM6 in pan-cancer inspired us to explore its further influence in tumor progression and its impact on disease prognosis." (PMID 35909893, 2022). "Results from the analysis provided evidence that THEM6‐deficient tumours display significantly less lipids and cholesterol than CTL tumours, thus confirming a role for THEM6 in the maintenance of the tumour lipidome." (PMID 35014179, 2022). "In patients, THEM6 expression correlated with tumour aggressiveness and was highest in treatment‐resistant tumours." (PMID 35014179, 2022). "Analysis of the PRAD TCGA data revealed that THEM6 mRNA expression was significantly higher in tumour tissue than in normal prostate epithelium." (PMID 35014179, 2022). "We further validated THEM6 as a prognostic factor in PCa by staining a second TMA composed of tumour biopsies from treatment‐naïve patients documented with a 20‐year follow‐up (n = 69, Table EV5)." (PMID 35014179, 2022). "Consistently, the effector genes of five tumor-associated TIICs (CD8+ T cells, macrophages, Th1 cells, dendritic cells, and NK cells) were also downregulated in the THEM6-high expression group." (PMID 35909893, 2022). "THEM6 deletion reduces in vivo tumour growth and restores castration sensitivity in orthograft models of CRPC." (PMID 35014179, 2022). "Similar to 22rv1 and LNCaP AI, THEM6 KO strongly impaired tumour growth following ADT in the CWR22res orthograft model." (PMID 35014179, 2022). "Immunohistochemistry (IHC) staining of prostate orthografts confirmed THEM6 over‐expression in CRPC tumours and highlighted strong cytoplasmic and perinuclear staining in tumour epithelial cells." (PMID 35014179, 2022). "CRPC and NEPC tumours exhibited significantly higher levels of the THEM6 protein than untreated tumours, with the highest score obtained for CRPC." (PMID 35014179, 2022). "In a xenograft model, THEM6 KO significantly reduced tumor volume and increased tumor sensitivity to ADT." (PMID 35107853, 2022). "In addition, the expression of THEM6 increased as the malignancy of the patient's tumor increased, as indicated by the TNM stage." (PMID 38081884, 2023).
tumor (continued). "Furthermore, the high expression group exhibited lower estimated fraction, immune fraction, and stromal fraction, indicating that THEM6 has a significant impact on the immune status of the tumor microenvironment." (PMID 38081884, 2023). "Moreover, in both patient cohorts, high THEM6 levels were significantly associated with high Ki67 expression, indicating that THEM6 is expressed at higher levels in highly proliferative tumours." (PMID 35014179, 2022). "Besides, in terms of the enrichment score in the THEM6-high expression group, it was higher in classical immune-inhibited oncogenic pathways and several tumor oncogenic genes, which led to ICB-related high progression of the disease." (PMID 35909893, 2022). "Previously, the authors had shown that ADT resistance was associated with rewiring of lipid metabolism, and hence, they hypothesized that THEM6 was involved in the maintenance of tumor lipidome." (PMID 35107853, 2022). "Strikingly, most of the UPR‐related genes were significantly enriched in high THEM6 tumours." (PMID 35014179, 2022). "Similarly, THEM6 KO significantly impaired the growth of LNCaP AI tumours developed in castrated mice." (PMID 35014179, 2022). "The authors further validated THEM6 overexpression in several tumour types, including prostate." (PMID 35014179, 2022). "Our study further explored the role of THEM6 in tumor immunologic mechanism." (PMID 35909893, 2022). "The immune-inhibited oncogenic pathways were associated with the noninflammatory TME, that was, a blockage of the formation of immune-inhibited carcinogenic pathways can improve the noninflammatory TME resulted by THEM6, so as to reactivate the immune system of the tumor and play a therapeutic role." (PMID 35909893, 2022). "Furthermore, THEM6 may influence macrophage recruitment and polarization in the tumor microenvironment by regulating CCL2 secretion, which in turn affects macrophage recruitment in the tumor microenvironment." (PMID 38081884, 2023).
cancer (4 papers, 2022 to 2024). A tumor composed of atypical neoplastic, often pleomorphic cells that invade other tissues. "Thioesterase superfamily member 6 (THEM6) has been implicated in the development and progression of various cancers." (PMID 35909893, 2022). "Next, we functionally tested the effect of THEM6 loss on de novo sterol biosynthesis by incubating cancer cells with [U13C]‐glucose and [U13C]‐glutamine and following 13C incorporation into sterols using GC‐MS." (PMID 35014179, 2022). "Pan-cancer analysis showed that the expression of THEM6 was associated with immunomodulators, such as immunostimulators, MHC molecules, chemokines, and receptors in most tumors, despite varied correlations among different cancers." (PMID 35909893, 2022). "According to the results, the expression of THEM6 was associated with the progression and prognosis of most types of cancers, including BLCA." (PMID 35909893, 2022). "In addition, THEM6 was negatively associated with the immune score and stromal score in most cancers." (PMID 35909893, 2022). "A study also demonstrated that knocking down THEM6 affects the synthesis of new sterols and fatty acids (FAs) in cancer cells." (PMID 38081884, 2023). "To further explore the variation of THEM6 in different tumors, we also examined its expression levels in various cancer types using the TCGA database in TIMER." (PMID 38081884, 2023). "Lately, THEM6 (C8orf55/DSCD75) has been found to be highly expressed in cancer cells, with its expression gradually increasing as the cancer progresses." (PMID 38081884, 2023). "Among these cohorts, only THEM6 showed a statistically significant difference with increased expression in carcinomas." (PMID 38081884, 2023). "Based on TCGA and GTEx databases, the expression differences of THEM6 were analyzed among 27 types of cancer and paracancerous tissues." (PMID 35909893, 2022). "Through pan-cancer analysis, clearly, THEM6 mRNA expression is upregulated in various cancer tissues and most cancer cell lines." (PMID 35909893, 2022). "Further correlation analysis was made between THEM6 gene expression and the score of these immune cells in 33 types of cancers." (PMID 35909893, 2022). "Firstly, a higher expression of THEM6 in cancer tissues was verified by exome sequencing analysis of the 12 pairs of matched cancer and adjacent normal tissues." (PMID 35909893, 2022). "Through pan-cancer analysis, we explored the THEM6 expression pattern and immunological role using The Cancer Genome Atlas (TCGA) database." (PMID 35909893, 2022). "Using tissue microarray (TMA), one prior study reported significant expression of THEM6 in various cancer tissues in comparison to normal tissues." (PMID 35909893, 2022). "To gain further insights into the role of THEM6 in cancer cells, we performed a proteomic comparison of 22rv1 cells proficient or depleted for THEM6." (PMID 35014179, 2022). "As for the cancer-immunity cycle, the activity of step 1 (release of cancer cell antigens) and step 4 (T cell recruiting) was downregulated in the THEM6-high expression group." (PMID 35909893, 2022). "Knockdown of THEM6 significantly altered the lipid composition of cancer cells." (PMID 38081884, 2023). "Meanwhile, it has been found that high expression of THEM6 in different cancer types may lead to different clinical outcomes." (PMID 35909893, 2022). "In our study, through pan-cancer analysis, a significant association of THEM6 gene with TIME was found, showing substantial negative correlation with BLCA TME, primarily noninflamed TME." (PMID 35909893, 2022). "Besides, its expression was also increased with the progression of cancer, signifying THEM6 as a potential candidate biomarker for some types of cancer." (PMID 35909893, 2022). "In particular, the inability of cancer cells to activate the ATF4/CHOP pathway was a constant feature of THEM6‐deficient PCa cancer cells, irrespective of their AR status." (PMID 35014179, 2022).
cancer (continued). "Both our study and this study have found low expression of THEM6 in some cancer tissues, but the significance of its low expression has not been studied yet." (PMID 35909893, 2022).
THEM6 also shares sentences with these, for which no sentence is quoted: cholangiocarcinoma (1 paper); colorectal cancer (1); gastric cancer (1); invasive breast carcinoma (1); lymph node metastasis (1); vascular cancer (1).